SIRPA (signal regulatory protein alpha)
Diseases named in the same sentence as SIRPA in open-access papers (continued):
Sharing a sentence is not in itself a finding about the gene and the disease.
acute myeloid leukemia (16 papers, 2013 to 2025). Acute myeloid leukemia (AML) is a group of neoplasms arising from precursor cells committed to the myeloid cell-line differentiation. "In the druggability evaluation, we found that drugs targeting SIRPA have been investigated in clinical trials for the treatment of cancers such as acute myeloid leukemia (evorpacept) and large B-cell lymphoma (maplirpacept)." (PMID 40299563, 2025). "A previous study showed that a novel human SIRPα-Fc fusion protein resulted in the preferential phagocytosis of acute myeloid leukemia with the blockade of CD47/SIRPα." (PMID 27671753, 2016). "In this study we aimed to determine the role of the SIRPα in acute myeloid leukemia." (PMID 23320069, 2013). "More recently, targeting CD47 by SIRPα-Fc fusion protein or monoclonal antibody combined with azacitidine showed reliable efficacy and safety in some malignant hematological tumors such as myelodysplastic syndrome, acute myeloid leukemia and chronic myelomonocytic leukemia in clinical trials." (PMID 38532108, 2024). "Targeting of the SIRPα/CD47 axis in the context of cancer using an anti-CD47 blocking antibody enhanced phagocytosis of acute myeloid leukemia (AML) cells." (PMID 31801627, 2019). "Recent studies show the importance of interactions between CD47 expressed on acute myeloid leukemia (AML) cells and the inhibitory immunoreceptor, signal regulatory protein-alpha (SIRPα) on macrophages." (PMID 23320069, 2013). "Comparing acute myeloid leukemia cases with normal bone marrow, lower expression of SIRPα was observed in immature AML subtypes, suggesting a myeloid differentiation stage-dependent expression, which is in line with the high expression of SIRPα found on normal monocytes and macrophages." (PMID 23320069, 2013). "Clinical studies confirm the importance of inhibiting the CD47/SIRPα interaction in various hematological malignancies, including myelodysplastic syndrome (MDS), acute myeloid leukemia (AML), and relapsed/refractory non-Hodgkin’s lymphoma (R/R-NHL)." (PMID 35978372, 2022).
lymphoma (16 papers, 2019 to 2024). A malignant (clonal) proliferation of B- lymphocytes or T- lymphocytes which involves the lymph nodes, bone marrow and/or extranodal sites. "The only “monotherapy” to succeed to date against patient tumors is an intratumorally administered SIRPα-IgG1 chimera in fungoides mycosis (a type of lymphoma), with evidence that the IgG1 serves to opsonize while SIRPα binds CD47." (PMID 35454837, 2022). "Lin and colleagues demonstrated that CD47 blockade ex vivo with TTI-621 (a fusion protein of an engineered SIRPα protein and human IgG1-Fc) on lymphoma cells triggered their phagocytosis by a broad subset of macrophages, including both the M1 and the M2 subtype." (PMID 34729396, 2021). "Similarly, mice treated with both rituximab and an anti-mouse SIRPα antibody reduced lymphoma growth in a xenograft model, resulting in prolonged survival." (PMID 33105656, 2020). "Together, these data confirmed the anti-lymphoma activity of HX009 across both the CD47+ B- and T-cell lymphomas, due to the contribution of the SIRPα fragment in HX009." (PMID 37012357, 2023). "Another study enrolled 14 patients with R/R lymphoma to evaluate the safety, tolerability, pharmacokinetics (PK), pharmacodynamics (PD), and clinical responses of IMM01 (SIRPα-IgG 1 fusion protein)." (PMID 35978372, 2022). "Correspondingly, SIRPα blocking agents also increased neutrophil-mediated anticancer effects, with antibody KWAR23 promoting the neutrophil-mediated phagocytic removal of lymphoma cells by rituximab and breast cancer cells by trastuzumab." (PMID 33105656, 2020). "Of note, it appeared that the ratio of lymphoma cells to macrophages was much higher in the RTX, SIRPα-Fc and RTX/SIRPα-Fc groups." (PMID 31611550, 2019). "Immunofluorescent staining in FL lymphoma tissue showed that while the majority of CD14+ cells were located around follicles, SIRPα+ cells resided both inside and outside of the follicles." (PMID 31611550, 2019). "The frequency of total SIRPα+ and CD14+ cells were significantly higher in patients with follicular grade 1/2 lymphoma by histology at diagnosis (Dx) than patients with FL grade 3a/3b." (PMID 31611550, 2019). "Using this assay, we investigated whether blocking the interaction between SIRPα and CD47 using SIRPα-Fc enhanced phagocytosis of lymphoma cells by Mo/MΦs." (PMID 31611550, 2019). "Thus, to determine whether hCD47 cross-dressing is mediated by binding of hCD47 to pig SIRPα, we performed cocultures with pig lymphoma cell line (LCL) cells that do not express SIRPα (right)." (PMID 36454036, 2022).
hepatocellular carcinoma (12 papers, 2014 to 2026). A malignant tumor that arises from hepatocytes. "SHP-1 and SHP-2 regulate SYK dephosphorylation through interactions with Siglec-5 and SIRPα, influencing cell signaling pathways and hepatocellular carcinoma progression." (PMID 40858654, 2025). "Overexpression of SIRPα alone in APL cells (HL-60 and NB4) or hepatocellular carcinoma Huh7 cells significantly increased cell apoptosis, strongly arguing that SIRPα is a general pro-apoptotic molecule functioning in various tumor cells." (PMID 27010069, 2016). "Previous studies by us and others showed that APL HL-60 cells and hepatocellular carcinoma Huh7 cells lack SIRPα protein expression." (PMID 27010069, 2016). "Consistent with the results from mouse studies, the treatment with anti‐SIRPα mAb significantly enhanced phagocytic activity of human macrophages against human hepatoma cell line, compared with that with isotype‐matched control Ab, whereas that with nti‐CD47mAb rather reduced." (PMID 30460349, 2018). "The interactions among Siglec-5, Siglec-14, SIRPα, SHP1, SHP2, SYK, and ROS create a complex regulatory network in hepatocellular carcinoma." (PMID 40858654, 2025). "In hepatocellular carcinoma (HCC), TSP1 can prevent the interaction between CD47 and SIRPα, disrupt the “don’t eat me” signal between hepatoma cells and macrophages, and prevent immune escape." (PMID 37829341, 2023). "We found that expression of SIRPα resulted in apoptosis both of APL HL-60 cells and hepatocellular carcinoma Huh7 cells possibly by suppressing β-catenin signal pathway and upregulating Foxo3a." (PMID 27010069, 2016).
B cell lymphoma (10 papers, 2019 to 2024). "Importantly, the ectopic expression of VISTA strongly reduced the surface levels of the phagocytosis checkpoint SIRPα and, in line with this, augmented basal levels of phagocytosis of a panel of B cell lymphoma cell lines." (PMID 38553748, 2024). "Given an extremely low frequency of CD14+ cells in biopsy specimens of B-cell NHL, we tested whether SIRPα was able to serve a marker for intratumoral Mo/MΦs." (PMID 31611550, 2019). "We previously showed that an antibody to SIRPα that blocks its interaction with CD47 markedly enhanced the inhibitory effect of rituximab, an antibody to human (h) CD20, on the growth of human B cell lymphoma in immunodeficient mice." (PMID 38162643, 2023). "A treatment combining anti-CD47 mAb with TTI-621, a SIRPα-Fc fusion protein used to prevent SIRPα:CD47 interaction, was reported to promote the phagocytosis of tumor cells in a B-cell lymphoma mouse model." (PMID 34638388, 2021). "Anti-CD47 antibody in combination with TTI-621, a SIRPα-Fc fusion protein that could block the binding between SIRPα and CD47, promotes phagocytosis of tumor cells in s B-cell lymphoma mouse model." (PMID 33251232, 2020). "Signal regulatory protein-α (SIRPα) is a key member of the “do-not-eat-me” signaling pathway, but its biological role and clinical relevance in B-cell NHL is relatively unknown." (PMID 31611550, 2019).
lung cancer (10 papers, 2017 to 2025). A malignant neoplasm involving the lung. "This study aimed to explore into the role and underlying molecular mechanisms of SIRPα in lung cancer growth." (PMID 36419386, 2023). "Therefore, endurance exercise-induced elevated SIRPα in lung cancer tissues is associated with a decrease in the tumor phagocytic ability of TAMs." (PMID 36186906, 2022). "A mouse model with lung cancer in wild‐type (WT) and SIRPα‐knockout mouse (KO) mice was established by subcutaneous injection of Lewis murine lung cancer cells (LLC)." (PMID 36419386, 2023). "Blocking antibodies that dismiss the interaction between CD47 and SIRPα enable the phagocytosis of lung cancer cells and CSCs in vitro and inhibited tumor growth in several xenotransplantation models." (PMID 28484448, 2017). "Disruption of the CD47–SIRPα interaction with anti-human or anti-mouse SIRPα antibody also resulted in significant phagocytosis of lung cancer cells." (PMID 28484448, 2017). "Finally, we evaluated the characteristics of SIRPα expression in human lung cancer by gene expression profiling interactive analysis database (GEPIA)." (PMID 36419386, 2023). "Thereby, we confirm that SIRPα is a useful target in the treatment of lung cancer." (PMID 36419386, 2023). "Endurance exercise combined with targeting PD-L1, SIRPα and reprogramming TAMs from M2 to M1 type may be an effective strategy for immunotherapy in lung cancer patients." (PMID 36186906, 2022). "We in this study, for the first time, investigated the role of SIRPα in SIRPα knock‐out (KO) mice and found that lack of SIRPα significantly reduced lung cancer cell growth in mice, in association with improved MPs and neutrophils (NPs) phagocytosis and reduced IL‐6 expression in tumour tissues." (PMID 36419386, 2023). "Therefore, high expression of these molecules predicts a poor prognosis, and SIRPα could be a promising prognosis biomarker in patients with lung cancer." (PMID 36419386, 2023). "SIRPα could be a useful target in immunotherapy of lung cancer." (PMID 36419386, 2023). "Notably, the level of SIRPα in lung cancer tissue was significantly higher than that in healthy lung tissue, while endurance exercise also significantly up-regulated the level of SIRPα in lung cancer tissue." (PMID 36186906, 2022). "We infected the lung cancer epithelial cell line A549 with EBOV GP and U2OS cells with VSV G and MACV GP pseudoviruses, after siRNA-mediated knockdown of SIRPA." (PMID 34097709, 2021). "Taken together, we in this study conclude that lack of SIRPα attenuated lung cancer growth in mice by reducing SHP‐1/STAT3/p38 MAPK signalling, subsequently suppressing IL‐6 expression, meanwhile improving M1 and N1 subtypes and their phagocytosis activity." (PMID 36419386, 2023). "Lack of SIRPα suppressed lung cancer cell growth in mice, dependent on circulating macrophages and neutrophils, in association with improved phagocytosis and reduced IL‐6 expression." (PMID 36419386, 2023). "Additionally, immunohistochemistry staining results validated from the Human Protein Atlas database revealed the CD47, CD73, SIRPA, and TIM-3 protein to be upregulated in lung cancer tissues compared to normal lung tissues." (PMID 34135424, 2021). "However, the role and downstream signalling pathways of SIRPα in the progression of lung cancer are not well studied so far." (PMID 36419386, 2023). "However, the role of SIRPα signalling in the progression of lung cancer is not well investigated so far." (PMID 36419386, 2023).
osteosarcoma (10 papers, 2019 to 2026). A usually aggressive malignant bone-forming mesenchymal neoplasm, predominantly affecting adolescents and young adults. "Specifically, in osteosarcoma cells, the upregulation of SIRPα activates the extracellular signal-regulated kinase (ERK) pathway, leading to the phosphorylation of specificity protein 1 (Sp1) at the threonine 278 site." (PMID 40589735, 2025). "SIRPA was also positively correlated with PD-L1 expression in TAMs in osteosarcoma, myxofibrosarcoma, dedifferentiated liposarcoma, and SS." (PMID 37958467, 2023). "SIRPA+ TAM infiltration in osteosarcoma and chondrosarcoma was less common (respectively, observed in around 30% and 2% of all cases)." (PMID 37958467, 2023). "In vivo, in an immune-competent murine F420 osteosarcoma model SIRPα-Fc-VV had greater anti-tumour activity than YFP-VV and SIRPα-VV resulting in significant animal survival." (PMID 36140243, 2022). "CD47 expression was observed in approximately 53% of osteosarcoma cells, whereas SIRPα expression was identified in approximately 32% of the infiltrating macrophages." (PMID 33802565, 2021). "Accordingly, other authors have described that silencing or blocking of SIRPα in RAW264.7 macrophages promoted the phagocytosis of osteosarcoma cancer cells." (PMID 32231135, 2020). "CD47 is a cell-surface molecule on osteosarcoma cells that function as a “don’t eat me” signal by engaging signal-regulatory protein alpha (SIRPα), an inhibitory receptor on macrophages." (PMID 30674867, 2019). "Moreover, SIRPA-mediated inhibition occurred in U2OS (osteosarcoma), 293T (kidney epithelia) and A549 (lung epithelia), suggesting that this inhibition is not restricted to a specific cell type." (PMID 34097709, 2021). "Although there are limited studies on anti-CD47/SIRPα therapy in osteosarcoma, these suggested strategies targeting CD47/SIRP-α that turn the ‘don’t eat me’ signal off may be an efficient therapy in osteosarcoma." (PMID 33363016, 2020). "Although the prognostic relevance of CD68+ and CD163+ macrophage infiltration in osteosarcoma was not described, lower SIRPα levels were associated with a worse overall survival among non-translocation sarcomas, and CD47 expression turned out to be a poor prognostic factor in osteosarcomas." (PMID 33802565, 2021).
Thrombocytopenia (10 papers, 2009 to 2025). A reduction in the number of circulating thrombocytes. "Moreover, thrombocytopenia was a common treatment emergent adverse event among patients treated with ontorpacept, another SIRPα-Fc decoy receptor." (PMID 40078999, 2025). "While targeting SIRPα has shown success in eliminating the thrombocytopenia associated with CD47-targeting agents, the strategy still presents a risk through potential binding of these antibodies to SIRPβ and SIRPγ, which have high sequence homology to SIRPα in the extracellular domain." (PMID 40408355, 2025). "It is anticipated that using anti-SIRPα to target the SIRPα/CD47 axis may have a beneficial safety profile due to SIRPα’s more constrained expression, which can lower the risk of adverse events such as acute anemia, thrombocytopenia caused by anti-CD47." (PMID 37345054, 2023). "As expected from the physiology of CD47 expression, hematologic changes were the most common grade 3 or higher TRAEs; neutropenia (6.5%) and thrombocytopenia (8.3%) were the most common in anti-CD47 mAbs and selective SIRPα blockers, respectively." (PMID 36439116, 2022). "Compared with SIRPα-Fc fusion proteins, an anti-SIRPα antibody, such as BMS-986351, provides a higher-affinity blocking capability to CD47, has single-agent activity, and has shown minimal impact on hematologic parameters, including thrombocytopenia." (PMID 38319147, 2024).
Autoimmunity (9 papers, 2016 to 2024). The occurrence of an immune reaction against the organism's own cells or tissues. "Immune inhibitory surface proteins such as CTLA4, CD47, and SIRPα, among many others, provide a means for limiting autoimmunity." (PMID 38543910, 2024). "Altogether, these data suggest that SIRPα:CD47 signaling is particularly important for regulating immune responses in the context of cancer, infectious challenge and potentially, β-cell stress in subjects with high genetic risk for autoimmunity and specifically, T1D." (PMID 34603322, 2021). "As another possible explanation, Sirpα-polymorphisms among the different (individual) donor macrophages could have differential levels of phagocytosis as it has been previously shown that polymorphism in SIRPα controls CD47 binding and autoimmunity." (PMID 27092773, 2016). "In fact, the mere depletion of SIRPα without RT is ineffective, as evidenced by Sirpα−/− mice exhibiting neither inherent autoimmunity nor innate resistance to tumor engraftment and growth." (PMID 34050181, 2021).
pancreatic cancer (9 papers, 2021 to 2025). "For this purpose, we studied the effects of an anti-BAG3 and an anti-SIRPα antibody, separately or in combination, in a murine model of pancreatic cancer orthotopic allografts in syngeneic immunocompetent animals." (PMID 35241649, 2022). "In conclusion, our findings show that the blockades of BAG3/BAG3R and SIRPα/CD47 axes converge in eliciting a sound anti-tumor immune response against pancreatic cancer and in countering tumor growth and the metastatic process." (PMID 35241649, 2022). "The BAG3- and SIRPα- mediated pathways trigger distinct cellular targets and signaling mechanisms in pancreatic cancer microenvironment." (PMID 35241649, 2022). "Hence, our data supports the further development of a SIRPα-αMSLN LicMAb for evaluation in early clinical trials on advanced ovarian and pancreatic cancer patients." (PMID 40402266, 2025). "For pancreatic cancer (Pan02 and KPC) growth data in WT and SIRPα−/− mice, we fit c1, cmax, and A." (PMID 41296731, 2025). "In addition, we use growth data from pancreatic cancer cell lines Pan01 and KPC in WT and SIRPα−/− mice." (PMID 41296731, 2025). "In the pancreatic cancer microenvironment, two distinct mechanisms involved in supporting tumor growth and suppressing the anti-tumor immune response are mediated by BAG3/BAG3R and SIRPα/CD47 axes." (PMID 35241649, 2022). "This study found SIRPα, LILRB1, and SIGLEC-10 to be increased in pancreatic cancer tissues." (PMID 34778091, 2021).
Alzheimer disease (8 papers, 2017 to 2025). A progressive, neurodegenerative disease characterized by loss of function and death of nerve cells in several areas of the brain leading to loss of cognitive function such as memory and language. "Overexpression of CD47 inhibits microglia engulfment in ASD, whereas the loss of its microglial receptor, Signal Regulatory Protein Alpha (SIRPα), enhances synaptic pruning in Alzheimer’s disease (AD)." (PMID 40238451, 2025). "To investigate the role of SIRPα in neurodegeneration, we modulate the expression of microglial SIRPα in mouse models of Alzheimer’s disease." (PMID 33795678, 2021). "In human tissue, we observe that microglial SIRPα expression declines alongside the progression of Alzheimer’s disease." (PMID 33795678, 2021). "Here, the authors show microglial SIRPα declines in the model of Alzheimer’s disease, leading to excessive microglia mediated synapse elimination as well as impaired cognitive function." (PMID 33795678, 2021). "CD172a, also known as the signal regulatory protein A (SIRPa), is an inhibitory receptor that binds to “do not eat me” ligand CD47 on healthy neurons and loss of CD172a from microglia have led to synaptic pruning in mouse models of Alzheimer’s disease." (PMID 39334169, 2024). "In light of the key role of SIRPα in mediating the phagocytosis of apoptotic cells and its possible involvement in the clearance of amyloid-β plaques in Alzheimer’s disease, in the present study we set out to investigate the possible involvement of SIRPα in prion pathogenesis in vivo." (PMID 28545141, 2017).